MIR1227 (microRNA 1227)
Synonyms: hsa-mir-1227; MIRN1227; mir-1227
Gene: MicroRNA gene on chromosome 19 (2,234,062 to 2,234,149, reverse strand). Ensembl gene ENSG00000221411.
Gene Ontology:
Biological process: miRNA-mediated post-transcriptional gene silencing
Cellular component: RISC complex